PGF (placental growth factor)
Diseases named in the same sentence as PGF in open-access papers (continued):
Sharing a sentence is not in itself a finding about the gene and the disease.
preeclampsia (continued). "The placenta itself produces several angiogenic factors involved in endothelial growth and function, including vascular endothelial growth factor (VEGF) and placental growth factor (PlGF), both of which are decreased in preeclampsia (PE)." (PMID 38484284, 2024). "Previous studies have identified some biomarkers for the prediction of preeclampsia, such as sFlt-1, sFlt-1/placental growth factor (PlGF), mean arterial pressure (MAP), uterine artery pulse index (UtA-PI), and pregnancy-associated plasma protein A (PAPP-A)." (PMID 38879866, 2024). "In fact, the involvement of H2S production in plasma levels of sFLT1, PGF, and other molecules related to preeclampsia has already been demonstrated." (PMID 38276547, 2024). "Recent research revealed a link between an imbalance in angiogenic factors and early-onset preeclampsia, characterized by elevated levels of soluble fms-like tyrosine kinase-1 and decreased placental growth factor." (PMID 38798792, 2024). "Exercise increases apelin levels to reduce preeclampsia symptoms by increasing eNOS, NO, placental growth factor (PlGF), and VEGF and decreasing levels of fms-like tyrosine kinase 1 (sFlt-1), soluble endoglin (sEng), and oxidative stress." (PMID 37964253, 2023). "For example, Soluble fms-like tyrosine kinase 1 (sFlt-1) and Placental growth factor (PlGF) are assessed by some centers to evaluate the likelihood of preeclampsia development." (PMID 36180668, 2023). "A systematic review examined the performance of soluble fms-like tyrosine kinase-1 (sFlt-1), the placental growth factor (PlGF), and the sFlt-1/PlGF ratio in predicting adverse outcomes in women with preeclampsia." (PMID 36833689, 2023). "FLT1 encodes Fms-related tyrosine kinase 1 (FLT1 or VEGFR1), which is related to reactive oxygen species, and sFlt1, the soluble form of FLT1, is widely used for diagnosis and management in preeclampsia with placental growth factor (PIGF)." (PMID 37020283, 2023). "Various maternal serum biochemical indices, including activin A, inhibin A, and placental growth factor, have been used to predict preeclampsia; however, the predictive value of these indices is low." (PMID 37761261, 2023). "There is very little information in the contemporary literature on the relationship between melatonin levels and the placental growth factor PlGF, which is important in the pathogenesis of preeclampsia development." (PMID 37168313, 2023). "The expression patterns of VEGF, placental growth factor, and VEGF-1 are altered in preeclampsia, with placental growth factor, a vital angiogenic protein for fetal angiogenesis, being notably reduced." (PMID 37987269, 2023). "Soluble fms-like tyrosine kinase-1 (sFlt-1) and placental growth factor (PlGF) level changes are noticeable several weeks before the onset of preeclampsia and its related complications." (PMID 35275947, 2022). "Among the other known biomarkers of preeclampsia—sFLT-1, pregnancy-associated plasma protein A (PAPP-A), placental growth factor (PIGF), and endoglin (ENG)—PIGF and PAPP-A were indeed significantly different between normotensive and preeclamptic women." (PMID 36569558, 2022). "Serum markers which are routinely used to predict preeclampsia in the first trimester are Pregnancy Associated Plasma Protein-A (PAPP-A), Beta Human Chorionic Gonadotropin (Beta-HCG) and Placental Growth Factor (PlGF)." (PMID 35887927, 2022). "sFlt-1 and placental growth factor (PlGF) are well known markers of placental hypoxia and predictors of preeclampsia (PE)." (PMID 36429772, 2022). "The aim of this study was to determine the usefulness of placental growth factor (PlGF) and soluble fms-like tyrosine kinase-1 (sFlt-1) in predicting the time for pregnancy termination in pregnant women with known preeclampsia (PE) onset." (PMID 35795634, 2022).
preeclampsia (continued). "These paradigm-shifting studies build on earlier insights, again from this group, implicating defects in VEGF and placental growth factor (PlGF) signaling in the pathophysiology of preeclampsia." (PMID 36250464, 2022). "Many studies indicate that statins, especially pravastatin increase the level of PlGF (placental growth factor), which lowers the level of sFlt-1 thus reversing the effects of anti-angiogenic factors which lead to preeclampsia." (PMID 36714131, 2022). "Vascular endothelial growth factor (VEGF), endoglin, and placental growth factor (PlGF) are angiogenic factors of major relevance regarding the etiology of preeclampsia." (PMID 35198246, 2022). "Levels of anti-angiogenic factor sFLT1 are elevated, and angiogenic factor PGF are reduced in the circulation of individuals whose pregnancies are complicated by preeclampsia." (PMID 36139751, 2022). "For vascular biomarkers, numerous studies confirmed that placental growth factor (PlGF) had the function of regulating placental trophoblast and endothelial cells, and had a good predictive value for preeclampsia." (PMID 36386527, 2022). "Two of these proteins were proved to play a role in preeclampsia (PE) development in singleton gestation: placental growth factor (PlGF) and serum soluble fms-like tyrosine kinase-1 (sFlt-1)." (PMID 34438609, 2021). "Soluble fms-like tyrosine kinase 1 (sFlt-1), placental growth factor (PlGF), and vascular endothelial growth factor (VEGF) have been shown to play a pathogenic role in the development of preeclampsia." (PMID 33727707, 2021). "Functional enrichment analysis of the 447 human-upregulated DEGs, including ADAM12, ERVW-1, KISS1, LGALS13, PAPPA2, PGF, and SIGLEC6, revealed over-representation of genes implicated in preeclampsia and other pregnancy disorders." (PMID 34154587, 2021). "Expression of placental growth factor (PlGF) precede preeclampsia by several weeks and its expression decreases in preeclampsia." (PMID 33653375, 2021). "Circulating levels of placental growth factor (PlGF), another proangiogenic protein, are decreased in preeclampsia." (PMID 34042284, 2021). "We next assessed the effects of NR4A2 knockdown on sFlt-1, an anti-angiogenic factor increased in preeclampsia, and placental growth factor (PGF), an angiogenic factor decreased in preeclampsia." (PMID 34667209, 2021). "This prospective observational cohort study has used T2-weighted imaging, T2* mapping and maternal PlGF (placental growth factor) concentrations to quantitatively demonstrate a placental phenotype in preeclampsia." (PMID 32336233, 2020). "To date, the most studied biomarker in preeclampsia is Placental Growth Factor (PlGF), the levels of which tend to drop in a sub-group of women destined to develop preeclampsia, and which has some demonstrated risk prediction potential." (PMID 33370367, 2020). "The aim of this systematic review was to determine the pathogenic role of soluble soluble fms-like tyrosine kinase-1 (sFlt-1) and placental growth factor (PlGF) in the prediction of preeclampsia in women." (PMID 31435580, 2019). "The most promising foetal and placental biomarkers for identifying preeclampsia are placental growth factor (PlGF) and soluble Flt-1 (sFlt-1), which are discussed subsequently." (PMID 31590294, 2019). "The ratio of soluble fms-like tyrosine kinase-1 to placental growth factor (sFlt-1/PlGF) is elevated and proved to be useful in preeclampsia (PE) diagnosis." (PMID 31396294, 2019). "The purpose of the present study was to explore the predictive effects of soluble fms‐like tyrosine kinase‐1 (sFlt‐1) and placental growth factor (PlGF) for preeclampsia." (PMID 30758082, 2019). "Placental growth factor (PlGF) and soluble fms-like tyrosine kinase-1 (sFlt-1), which both derive from the placenta, are biomarkers for preeclampsia with PlGF as one of the most highly modulated maternal blood proteins during the gestational age span." (PMID 31690271, 2019).
preeclampsia (continued). "In particular, studies have shown that the ratio of soluble fms-like tyrosine kinase-1 (sFlt-1) to placental growth factor (PlGF) is elevated in preeclampsia and is raised even before clinical onset of the disease." (PMID 31485276, 2019). "Placental growth factor (PlGF) has also been studied as a potential therapeutic option to correct the angiogenic imbalance that occurs during preeclampsia." (PMID 30144822, 2018). "Serum and placental samples from four groups of cases; normal term, IUGR, early-onset and late-onset preeclampsia, were analyzed for 25(OH)D vitamin D, sFLT1, PGF, LGALS13 in serum and vitamin D receptor (VDR), MAP1LC3B and BECN1 in placental tissues." (PMID 30408071, 2018). "We sought to assess the ratio of sFlt-1 (soluble fms-like tyrosine kinase 1) to PlGF (placental growth factor) in maternal serum as a screening test for preeclampsia in unselected nulliparous women with a singleton pregnancy." (PMID 28167687, 2017). "The use of the soluble fms-like tyrosine kinase 1/placental growth factor test influenced clinical decision making towards appropriate hospitalization in a considerable proportion of women with suspected preeclampsia." (PMID 27243815, 2016). "First-trimester serum PGF levels of women who developed preeclampsia were significantly lower than in women with normal pregnancies (115.72±32.55 vs. 217.30±74.48 pg/ml, P<0.001)." (PMID 25906026, 2015). "First trimester serum PGF levels of participants who developed preeclampsia were significantly lower compared with participants who had normal pregnancies." (PMID 25906026, 2015). "In humans, serum levels of the angiogenic placental growth factor (PIGF) are reduced in women with preeclampsia." (PMID 24367379, 2013). "Changes in maternal concentrations of the anti-angiogenic factors, soluble fms-like tyrosine kinase 1 (sFlt1) and soluble endoglin (sEng), and the pro-angiogenic placental growth factor (PlGF) precede the development of preeclampsia in healthy women." (PMID 20967275, 2010). "Low levels of placental growth factor (PlGF) and an elevated soluble fms-like tyrosine kinase-1 to PlGF (sFlt-1/PlGF) ratio are more characteristic of preeclampsia, whereas their preservation may indicate complement-mediated aHUS." (PMID 40722309, 2025). "Even 80–90% of women with EO-PE have abnormal maternal plasma soluble Fms-like Tyrosine Kinase-1-to-placental growth factor (sFlt-1:PlGF) or placental growth factor-to-soluble Endoglin (PlGF:sEng) ratios; this imbalance affects only 40–50% of patients with late-onset preeclampsia." (PMID 40649927, 2025). "Additionally, the soluble fms-like tyrosine kinase 1-to-placental growth factor (sFLT-1/PLGF) ratio is a key biomarker for diagnosing early- and late-onset preeclampsia." (PMID 40585732, 2025). "Currently, first-trimester combined screening—incorporating maternal risk factors, mean arterial pressure (MAP), uterine artery pulsatility index (UtA-PI), and placental growth factor (PlGF)—is regarded as one of the most effective strategies for predicting preeclampsia (PE)." (PMID 40283037, 2025). "Finally, offspring exhibited placental dysfunction, including impaired vascularization, abnormal fetoplacental ratios, downregulation of placental growth factor (PLGF), and upregulation of biomarkers used in human preeclampsia screening." (PMID 40906193, 2025). "The risk of preeclampsia, assessed by a score that includes clinical data, blood pressure, Doppler of the uterine arteries and laboratory results [pregnancy-associated plasma protein-A (PAPP-A) and placental growth factor (PlGF)], revealed a low risk." (PMID 39114649, 2024). "In addition to observing increased concentrations of sFLT1 in preeclampsia, a parallel decrease was noted in detectable circulating concentrations of placental growth factor (PlGF), a second circulating member of the VEGF family." (PMID 39087479, 2024).
preeclampsia (continued). "It is, however, known that women with preeclampsia have an imbalance of angiogenic markers in their blood, characterized by an elevated sFlt-1 (soluble fms-like tyrosine kinase-1) concentration and a decreased PlGF (placental growth factor) concentration." (PMID 38361240, 2024). "Otherwise, the screening process combines maternal risk factors with mean arterial pressure (MAP), serum placental growth factor (PlGF), pregnancy-associated plasma protein A (PAPP-A), and uterine artery pulsatility index (UTPI) to identify women at high risk of developing preeclampsia (PE)." (PMID 39857636, 2024). "Similarly, when paired with other screening approaches, biomarkers like as soluble FMS-like tyrosine kinase 1 (sFlt-1) and placental growth factor (PlGF) can improve the accuracy of preeclampsia identification." (PMID 38957710, 2024). "In addition, other placental markers have been described as abnormal in the case of fetal aneuploidy and have also been proposed in the screening of preeclampsia such as placental growth factor (PlGF)." (PMID 37108840, 2023). "As plasma TFPI is increased and placental growth factor (PlGF) is decreased in women with preeclampsia, the TFPI-to-PlGF ratio may be useful as a predictive marker for early prediction of preeclampsia." (PMID 37238908, 2023). "Similarly, the placental growth factor (PlGF) and soluble fms-like tyrosine kinase-1 (sFlt-1) commonly used in predicting preeclampsia were also demonstrated to be useful in screening for fetal Hb Bart’s disease." (PMID 36982732, 2023). "Besides, nearly one-third of the cases had fetal growth restriction, the decreased levels of placental growth factor (PLGF) were correlated with early onset preeclampsia and adverse pregnancy outcomes." (PMID 37596554, 2023). "The expression and release of chemerin increases in the placenta of women with preeclampsia and are positively correlated with the ratio of soluble Fms-like tyrosine kinase-1 (sFlt-1) to placental growth factor (PlGF), a commonly used biomarker of preeclampsia." (PMID 37964253, 2023). "The most promising markers for earlier diagnosis of preeclampsia is soluble endoglin (sEng), pregnancy-associated plasma protein-A (PAPP-A), soluble fms-like tyrosine kinase 1 (sFlt-1), and placental growth factor (PlGF)." (PMID 35089126, 2022). "Here, we examined whether the proton pump inhibitor omeprazole could acutely reduce sFlt-1 and ET-1 (measured as CT-proET-1 [C-terminal pro-endothelin-1]), or increase free PlGF (placental growth factor) in 20 women with confirmed preeclampsia." (PMID 35341328, 2022). "Preeclampsia, a hypertensive disorder occurring during pregnancy, is characterized by excessive oxidative stress and trophoblast dysfunction with dysregulation of soluble Fms-like tyrosine kinase 1 (sFlt-1) and placental growth factor (PlGF) production." (PMID 33673360, 2021). "For biomarkers of preeclampsia, combining AI and PS led to the reversal of the altered levels of creatine kinase, lactate dehydrogenase, cardiac troponin, soluble Fms-Like Tyrosine Kinase-1, and placental growth factor." (PMID 34940291, 2021). "Additionally, in preeclampsia, circulating maternal anti-angiogenic factors, such as soluble fms-like tyrosine kinase 1 (sFlt-1), are increased, and placental growth factor (PlGF) levels are decreased." (PMID 34882742, 2021). "Clinically employed screening tests based on angiogenesis-related biomarkers (eg, soluble fms-like tyrosine kinase 1 [sFlt-1] and placental growth factor [PlGF]) are able to predict the onset of preeclampsia only a few weeks before presentation of clinically obvious preeclampsia." (PMID 32617576, 2021). "The ratio between antiangiogenic biomarkers such as soluble FMS-like tyrosine kinase-1 (sFLT1) and angiogenic markers such as placental growth factor (PLGF) was demonstrated to usefully predict preeclampsia in gestations complicated by hypertension and the need for more or less urgent action." (PMID 33460427, 2021).
preeclampsia (continued). "The ratio of sFlt1 to placental growth factor has been used to predict preterm preeclampsia." (PMID 33670947, 2021). "This study aimed to evaluate the correlation between ophthalmologic factors and the serologic indicator soluble fms-like tyrosine kinase 1 (sFlt-1): placental growth factor (PlGF) ratio in patients with preeclampsia using optical coherence tomography (OCT) and OCT angiography (OCT-A)." (PMID 34882742, 2021). "Excess placental production of soluble fms-like tyrosine kinase (sFLT1), an antagonist of vascular endothelial growth factor (VEGF) and placental growth factor (PlGF) has been shown to be associated with decreased circulating levels of VEGF and PlGF in preeclampsia patients." (PMID 32179765, 2020). "However, data on VEGF and PGF expression in normal pregnancy and preeclampsia are still controversial as their mRNA levels have been reported to be decreased, increased or unchanged in preeclamptic placental tissue." (PMID 33396613, 2020). "The excessive soluble fms-like tyrosine kinase (sFlt)-1 or endoglin and the reduced free placental growth factor (PlGF) constitute another hypothesis for the pathogenesis of preeclampsia, namely, the angiogenic imbalance." (PMID 29367581, 2018). "Vascular endothelial growth factor (VEGF), placental growth factor (PlGF) and soluble fms-like tyrosine kinase (sFlt-1) play key roles in angiogenesis and neurogenesis and have therefore been extensively studied in preeclampsia." (PMID 30487752, 2018). "Higher levels of soluble fms-like tyrosine kinase 1 (sFlt-1) and soluble endoglin (sENG), as well as lower levels of placental growth factor (PlGF) were demonstrated before and after preeclampsia onset, making of these molecules good candidates for the early diagnosis of this syndrome." (PMID 28860607, 2017). "Elevated levels of the anti-angiogenic factors antagonize the effects of the pro-angiogenic factors, vascular endothelial growth factor (VEGF) and placental growth factor (PlGF) leading to widespread endothelial dysfunction and the clinical features of preeclampsia." (PMID 28199380, 2017). "Indeed, maternal serum PGF levels are significantly reduced in clinically evident cases of preeclampsia." (PMID 25906026, 2015). "Recent data has indicated that a direct screen including maternal characteristics, PAPP-A, placental growth factor (PlGF), uterine artery doppler pulsatility index and mean arterial pressure can identify over 90% of early-onset preeclampsia pregnancies in the first trimester." (PMID 26237472, 2014). "An imbalance of circulating angiogenic and antiangiogenic factors, including raised soluble fms-like tyrosine kinase-1 (sFlt-1) and decreased placental growth factor (PlGF), has been found in women diagnosed with preeclampsia and before clinical onset of the disease." (PMID 25230734, 2014). "Blood concentrations of sFlt1, a soluble VEGF receptor produced during pregnancy that binds VEGF and placental growth factor (PlGF), increase during the last 2 months of normal pregnancy and attain much greater levels in women with preeclampsia or gestational hypertension." (PMID 22097923, 2012). "Although circulating PGF, sFlt1, and sEng levels have been shown to be important markers of preeclampsia, no causal mutations in these genes associated with preeclampsia have been identified so far." (PMID 22685661, 2012). "It has been shown that levels of soluble fms-like tyrosine kinase (sFlt1) and soluble endoglin (sEng) are elevated while placental growth factor (PlGF) are reduced in women with diagnosis of preeclampsia and these levels correlate with disease severity and gestational age." (PMID 23110221, 2012). "Prior studies show that there is an angiogenic factor imbalance with elevated levels of antiangiogenic proteins soluble fms-like tyrosine kinase 1 (sFlt1) and soluble endoglin (sEng) and reduced levels of the proangiogenic protein, placental growth factor (PlGF) in women with preeclampsia." (PMID 22567501, 2011).